HIF1A (hypoxia inducible factor 1 subunit alpha)
Diseases named in the same sentence as HIF1A in open-access papers (continued):
Sharing a sentence is not in itself a finding about the gene and the disease.
cancer (continued). "HIF-1α is required for cardiac and vascular development and is a transcriptional factor responsive to PI3K–Akt activity in cancer cells." (PMID 29435158, 2018). "Although HIF-1α acts as a key factor regulating hypoxia response and glucose metabolism in cancer biology, the relationship between HOXA9 and HIF-1α-mediated hypoxia response and metabolic regulation has rarely been explored, especially in cSCC." (PMID 29662084, 2018). "Hypoxia triggers the stability of HIF-1α, which has previously been shown to induce EMT in cancer cells and promote metastasis." (PMID 29954442, 2018). "Based on previous studies, miR-31has been recognized as a potent cancer-related miRNA,involved in carcinogenesis of CRC by targeting tumorsuppressor genes such as HIF-1a and CDKN2B." (PMID 29633600, 2018). "This decreased the protein levels of HIF-1α and HIF-2α present in the cells, reducing the expression of HIF-1α target genes such as VEGF-A and GLUT1, and serving as both an anti-cancer and anti-angiogenesis agent." (PMID 30002330, 2018). "Both HIF-1α and HIF-2α are considered master sensors of hypoxia and are overexpressed in different types of cancer." (PMID 30200585, 2018). "Meanwhile, HIF-1α is frequently induced through EGFR activation and mediates carcinoma angiogenesis as well as promotes EMT and metastasis." (PMID 29499765, 2018). "Results from our MTA1 ChIP‐Seq analysis along with VEGF‐c and IL‐1β10, identified HIF‐1α as a novel transcriptional target of MTA1 in PCa, emphasizing the importance of MTA1 in the promotion of cancer angiogenesis and metastasis." (PMID 29024573, 2017). "Collectively, this work demonstrates that the hypoxia-responsive lncRNAs can be regulated at transcription level directly by HIF-1α and/or HIF-2α in a variety of cancers." (PMID 28789687, 2017). "Many of these genes are regulated by HIF-1α; therefore, HIF-1α has emerged as an attractive target for the development of novel cancer therapeutics." (PMID 27999195, 2017). "HIF-1α regulates HIF-1 transcriptional activity and activates multiple target genes that involve in crucial aspects of cancer progression, including angiogenesis, glucose metabolism, cell proliferation/ survival and apoptosis." (PMID 29100347, 2017). "Artemisinin reduces the levels of factors critical for angiogenesis, such as HIF-1α and VEGF, impeding the supply of cancer environmental factors to cancer cells." (PMID 28737711, 2017). "We also detected hypoxia-inducible factor 1-α (HIF1α) and organic anion-transporting polypeptides (OATP) expression, which are considered to increase dye uptake in cancer cells in different tissue samples." (PMID 28635650, 2017). "By disrupting the balance between HIF-1α and HIF-2α upon longer exposure of hypoxia, HAF leads to a highly aggressive cancer phenotype." (PMID 28572533, 2017). "SPHK-1 is known to regulate HIF-1α expression under hypoxia, and it is reported that SPHK-1 is a new target for cancer therapy." (PMID 28165392, 2017). "Hypoxia helps cancer cells to resist chemotherapy, whereas HIPK2 mediated repression of HIF-1α activity confers sensitization of chemoresistant cells with drug induced apoptosis." (PMID 28107201, 2017). "Several studies have defined the targets of miR-138 such as VIM, RhoC, Hif-1α, CCND1 and Sirt1 in cancer types other than RCC, which are often involved in cell migration, EMT, DNA damage repair, senescence." (PMID 28978010, 2017). "Hypoxia inducible factor 1 (HIF-1), is composed of HIF-1α and HIF-1β and is overexpressed in human malignant tumors." (PMID 28968982, 2017). "Cancer glycolysis is regulated by hypoxia inducible factor (HIF) and LDH-A is a known target of HIF-1a." (PMID 28946660, 2017).
cancer (continued). "HIF-1α then dimerizes with HIF-1β to recruit co-activators and drive transcription of many genes critical for key aspects of cancer pathogenesis." (PMID 28380438, 2017). "In our experimental model, cancer cells overexpressing STK33 and exposed to HSP90 inhibitor displayed a partial rescue of HIF-1α transcriptional activity and secreted VEGF-A." (PMID 29100402, 2017). "Upon activation of HIF-1α, an elevation of VEGF synthesis and secretion is essential for cancer angiogenesis and progression." (PMID 28710377, 2017). "By inhibiting STAT3, RNA-dependent protein kinase R (PKR), an eukaryotic initiation factor 2alpha (eIF2α) kinase, decreases HIF-1α and VEGF expression in cancer cells." (PMID 28978186, 2017). "Human HIF‐1α and HIF‐2α are upregulated in many cancers, promoting a procancer transcriptional program." (PMID 28401650, 2017). "In fact, Pro is reported to increase HIF-1α expression and transcriptional activity of HIF-1 in cancer cells." (PMID 28526934, 2017). "In cancer cells, the complexes containing STAT3, HIF-1α, CBP/p300, and Ref-1/APE bind to the Vegf promoter and increase VEGF expression." (PMID 28978186, 2017). "Under these conditions, HIF-1α heterodimerises with HIF-1β and binds to hypoxic response elements (HREs) in target genes, leading to the expression of proteins that help hypoxic cancer cells survive." (PMID 28476026, 2017). "Another example from cancer metabolism, is related to pyruvate dehydrogenase kinase 1 (PDHK1) which is also inducible by MYC and HIF-1α." (PMID 29257069, 2017). "Hypoxia protects cancer cells from chemotherapy induced apoptosis through both HIF-1α-mediated and HIF-1α-independent in HCC." (PMID 29088868, 2017). "These genes belong to relevant intracellular signaling pathways in cancer such as PI3K-Akt (COL4A2, MYC, PDGFA, SPP1), proteoglycans (HIF1A, MYC, PLAUR, TGFB1), and Hippo (CTGF, MYC, NF2, TGFB1)." (PMID 29075357, 2017). "HIF-1α induced by hypoxia has been found to promote upregulation of Snail and to attenuate the expression of E-cadherin, leading to EMT and increased cancer aggressiveness." (PMID 28468237, 2017). "Epigallocatechin can be considered as a pharmacologically effective compound to inhibit HIF-1a and LDH-A in cancer cells." (PMID 28946660, 2017). "From our study, we call for further researches of the molecular mechanisms of HIF1A location, which will likely provide new insights into the pivotal function of RBMS3 in cancer biology and should provide a novel approach to the treatment of GC." (PMID 27902480, 2017). "Thus, inhibiting HIF-1α activity may help enhance efficacy of conventional cancer therapy." (PMID 28107201, 2017). "HIF-1α and c-Myc can up-regulate transcription of GLUT1, sustaining the Warburg effect in cancer cells." (PMID 28881758, 2017). "PKM2 also has a dimeric form in cancer, which has a nuclear localization sequence allowing PKM2 to act as a co-transcription factor and kinase stimulating HIF-1α expression and activity." (PMID 28491867, 2017). "However, whether this HIF-1α–PPAR pathway occurs in cancer cells remains unclear (route 16)." (PMID 27589734, 2016). "In HT29 cancer cells, stimulation with PDGF and VEGF activated HIF1α; c-Myc was more activated during stimulation with PDGF and the inhibition of Akt showed a decrease in c-Myc activity." (PMID 27626684, 2016). "To determine the effects of hypoxia on HIF expression in cancer cells, we exposed MDA-MB-231 cells to normoxia (20% O2) or hypoxia (0.5% O2) for 24 h, and assessed HIF-1α and HIF-1β expression by immunoblot analysis." (PMID 27263528, 2016). "Our results support that Daxx can act as a repressor in controlling HIF-1α/HDAC1/Slug-mediated cancer cell invasion and is a potential therapeutic target for inhibition of cancer metastasis." (PMID 28004751, 2016). "Among HIF-1α targets there is the ABC glycoprotein transporter MDR1, which confers multidrug resistance on a variety of cancer cells." (PMID 27303923, 2016).
cancer (continued). "The activation of p70S6K1 affects the expression levels of two important angiogenesis-related downstream signaling molecules, HIF-1α and VEGF, which are involved in tumorigenesis and cancer development." (PMID 27765914, 2016). "The hypoxia-inducible factor (HIF1α), another key oncogenic TF, is functionally coordinated with c-MYC in controlling metabolic reprogramming in cancers." (PMID 27358718, 2016). "Thus, strategies targeting HIF-1α may be effective in cancer therapy." (PMID 26867977, 2016). "Observations that HIF-1α and HIF-2α can play different and often opposing roles in various malignancies is important as HIF inhibitors are systematically being developed as cancer therapies." (PMID 26837714, 2016). "In cancer cells, PKM2 has been shown to function as a coactivator of hypoxia-inducible factor 1-alpha (HIF-1α)." (PMID 27148264, 2016). "HIF-1α and VEGF are frequently shown to be overexpressed in numerous types of cancers and are known to be important regulators of angiogenesis." (PMID 26951793, 2016). "In cancer cells, expression of oxygen-regulated subunit (HIF-1α) is increased by either increased HIF-1α protein synthesis and stability or by increased mRNA levels." (PMID 27602585, 2016). "Most of the identified binding sites for HIF-1α on the promoter of HURP reside in highly methylated regions, known to be commonly inversely correlated with gene expression and gene methylation in cancer cells, including PCa cell lines." (PMID 27379206, 2016). "Angiogenesis, critically involved in cancer and AMD progression, can be augmented by the stimulation of KDM3A, KDM5B, and KDM6B, the expression of which is highly enhanced by HIF-1α." (PMID 27114850, 2016). "The induction of SENP3 in cancer cells initiates the angiogenic pathway; specifically SENP3 regulates the transcriptional activity of hypoxia-inducible factor 1α (HIF1α) via desumoylation of the co-regulatory protein p300." (PMID 27178176, 2016). "Specimens of HCC from cancer patients showed a general inverse correlation between miR-592 levels and the levels of WSB1 and HIF1α." (PMID 27542736, 2016). "Therefore, mitochondrial cholesterol loading may have an important role in cancer cell survival by a dual effect through impairment in mitochondrial function and dynamics, while promoting HIF1α stabilization via depletion of cytosolic 2-OG levels and generation of mitochondrial ROS." (PMID 27455839, 2016). "As hypoxia can promote EMT in many cancer cell types via HIF-1α induction, we treated FRO and sw579 cells with 0.1 mM CoCl2 or 1 mM dimethyloxalylglycine (DMOG, a HIF-1α degradation inhibitor)." (PMID 27487122, 2016). "Cancer cells take advantage of these pathways to further extend their survival advantages, such as activated PI3K/AKT/mTOR pathways, which can activate HIF-1α as previously discussed." (PMID 26962408, 2016). "As previousstudies have shown that inhibition of HIF-1α and HSP90 expressions have therapeuticimpact on cancer treatment, the inhibitory effect of LRS on expression of these genesimplies that this Lactobacillus can be used in treatment strategies." (PMID 27540529, 2016). "The positive feedback loop between HIF-1α and TGF-β functions in the regulation of cancer EMT and angiogenesis." (PMID 26989421, 2016). "The hypoxic cancer cells induce expression of the glucose importer GLUT1 and the lactate exporter MCT4, which is dependent on HIF1α." (PMID 27134166, 2016). "The aim of this study is to evaluate if the administration of acetylcysteine in combination with topotecan, can inhibit the cancer cell growth, due to changes in MCT4, CAV1 and HIF1A." (PMID 26859576, 2016). "It was reported that hypoxia-activated HIF-1α reduced E-cadherin expression and augmented MMP-2 expression during cancer cell migration." (PMID 26880989, 2016). "The critical role of hypoxia-inducible factor 1α (HIF-1α) and vascular endothelial growth factor (VEGF) are important in the cancer development." (PMID 26065676, 2015).
cancer (continued). "β2-M/HFE has been found to regulate negatively intracellular iron, activate HIF-1α and promote EMT in cancer cells." (PMID 25899529, 2015). "HIF1α and TWIST are two important EMT inducers in cancer cells, and TWIST is an important downstream effector of HIF1α." (PMID 26196741, 2015). "In summary, we obtained evidence that the HIF-1α-ILK regulatory loop plays a critical role in maintaining HIF-1α expression and regulating EMT in cancer cells via multiple mechanisms in a cell line- and cellular context-specific manner." (PMID 25821081, 2015). "FOXO3a upregulates miR-622 to repress HIF-1α expression via inactivation of ERK phosphorylation, resulting in the inhibition of the invasiveness of A549 cancer cells." (PMID 26528854, 2015). "In cancer cells of epithelial origin, hypoxia-induced EMT was mediated by transiently increased ROS at early stage and was sustained at late stage by HIF-1α-dependent expression of VEGF23." (PMID 26174737, 2015). "Despite these advances, caution must be exercised for the use of these inhibitors as a potential therapeutic strategy owing to the complex role of HIF-1α and HIF-2α in cancer." (PMID 25893706, 2015). "Although we have previously reported the constitutive activation of HIF-1α in normoxic cancer cells with a stable MDR phenotype, the parallel increase in HIF-1α transcription and the progressive acquisition of MDR is a new observation." (PMID 25686827, 2015). "Here, we provide novel evidence on the mechanisms by which copper triggers the EGFR/ERK/c-fos signalling cascade along with GPER and HIF-1α toward VEGF expression and function in cancer cells." (PMID 26415222, 2015). "Hazard ratio (HR) data for overall survival (OS), cancer-specific survival (CSS), and progression-free survival (PFS) with 95% confidence interval (CI) related to the expression status of HIF-1α or HIF-2α detected by immunohistochemistry were all extracted." (PMID 26402839, 2015). "The evidence for these molecules as reliable markers of hypoxia has been reviewed elsewhere and the overexpression of HIF-1α, CA9, GLUT1 and VEGF in various malignant tumors has also been demonstrated." (PMID 25789026, 2015). "They found that treatment of cancer cells with combination of curcumin and genistein led to angiogenesis inhibition by acting on VEGF protein expression via down regulation of HIF-1α and aryl hydrocarbon receptor nuclear translocator." (PMID 26006245, 2015). "As expected, large amounts of IL-6 were secreted by macrophages co-cultured with apoptotic MCF-7 cancer cells, accompanied by the phosphorylation of STAT3 and the upregulation of the mRNA levels of TGF-β1 and HIF-1α." (PMID 26016502, 2015). "Many target genes of STAT3 are involved in cancer, such as HIF-1α, which acts as an important factor in angiogenesis, and TGF-β1, which promotes cancer cell growth and metastasis." (PMID 26016502, 2015). "HIF-1α induced by hypoxia and growth factors has been shown to mediate EMT and metastasis of various cancer cells." (PMID 26520789, 2015). "HIF-1α and VEGF stained homogenously throughout the cancer nest, whereas CA-IX and GLUT-1 were localized in the center." (PMID 26622782, 2015). "We have previously demonstrated that, in mammalian cancer cell lines, TNF-α-induced NF-κB can increase HIF-1α mRNA, protein and activity levels, leading to transactivation of target genes in normoxia." (PMID 25510503, 2015). "Dysregulation of hypoxia-inducible transcription factors HIF-1α and HIF-2α correlates with poor prognosis in human cancers; yet, divergent and sometimes opposing activities of these factors in cancer biology have been observed." (PMID 25893706, 2015). "While HIF-1α is known to regulate proteolytic enzymes such as uPAR, cathepsins, MMP-1, MMP-2, MMP-9 in many cancer types, HIF-2α has directly been involved in membrane bound MT1-MMP in von Hippel-Lindau renal cell carcinoma." (PMID 26305551, 2015).
cancer (continued). "The antagonistic effects of HIF-1α and HIF-2α are important for the regulation of proliferation and apoptosis in cancer biology." (PMID 25625467, 2015). "Hypoxia is a prominent regulator of CXCR4 via HIF-1α, and inhibition of HIF-1α decreases the metastasis of cancers." (PMID 26176534, 2015). "Our results indicated that the aberrant expression of UCHL1 in cancer cells abrogated the VHL-mediated ubiquitination of HIF-1α, which led to the stabilization of HIF-1α and subsequent activation of HIF-1." (PMID 25615526, 2015). "MiR-373 up-regulates and activates two important EMT inducers, HIF1α and TWIST, by directly inhibiting TXNIP to drive cancer cell EMT." (PMID 26196741, 2015). "Our previous study revealed that, Q6, a novel analogue of TPZ, was capable of targeting hypoxic cancer cells, leading to the autophagic degradation of HIF-1α in the hypoxic HCC cells, with improved anti-cancer efficiency than its parental compound TPZ." (PMID 26649750, 2015). "We also noted decreased HIF-1α levels and increased expression of Redd1/DDIT4, a stress-activated protein, which is down regulated in a subset of human cancers and also controls mTOR complex activity." (PMID 25867026, 2015). "We propose that HIF-1α directly binds to the promoter of ZEB1 and serves as its critical positive regulator, thereby promoting EMT and cancer metastasis." (PMID 26057751, 2015). "In this regard, we demonstrated that a functional cooperation between HIF-1α and GPER contributes to VEGF regulation in cancer cells exposed to copper." (PMID 26415222, 2015). "Recently, some studies have shown that melatonin can decrease the expression of Hypoxia Inducible Factor 1 alpha (HIF-1α) and VEGF in various cancers." (PMID 24416386, 2014). "Molecules such as Her2, EGFR, VEGFR, ALK, AKT, p52, cyclin D1, Met, Cdk4, HIF-1α or MMP2 which play important roles as oncogenes and are involved in essential pathways of cancer are described to be client proteins of HSP90." (PMID 24978439, 2014). "We assessed the mechanisms of NIR dye uptake in canine and human cancer cells and tissues and demonstrated that NIR dye uptake and retention in cancer but not normal cells and tissues was likely mediated through the HIF-1α/OATPs signaling axis." (PMID 25361418, 2014). "Conversely, anticancer activities of NGAL have been demonstrated by its ability to inhibit the pro-neoplastic factor HIF-1a, the synthesis of HIF-1a-dependent VEGF, and phosphorylation of FAK kinase, as shown in colon, ovarian and pancreatic cancers." (PMID 24742531, 2014). "HIF-1α is constitutively expressed in most cells, whereas HIF-1α is inducible and is characteristically over-expressed in cancer cells during hypoxic conditions." (PMID 26932375, 2014). "Based on our results, we concluded that IMQ activates the STAT3 and PI3K/Akt pathways to increase HIF-1α expression at both the transcriptional and translational levels in TLR7/8-negative cancer cells." (PMID 24658058, 2014). "Potent oncogenes as c-Myc, HIF1α, Ras and PI3K/Akt are important promoters of cancer metabolic alterations." (PMID 24738035, 2014). "Effective knockdown of HIF-1α expression, as determined by reduced VEGF-A and Glut1 mRNA levels, resulted in significant decrease in NIR dye uptake and retention by canine cancer cells under hypoxia." (PMID 25361418, 2014). "The reported roles played by the HIF-1α subunit and HIF-1 transcription factor within the context of the hypoxic response in both healthy cells and cancer cells are very complex." (PMID 25350400, 2014). "HIF-1α and HIF-2α are broadly expressed in cancer cells, which are accounted for the vast majority of HIF-dependent effects." (PMID 24505470, 2014). "It had been previously reported that these molecules are natural enhancers of the expression of both HIF-1α and VEGF in cancer cells." (PMID 25093990, 2014). "HIF-1α, an upstream regulator of VEGF, triggers angiogenesis through VEGF in various types of cancer." (PMID 25058399, 2014).